APOB (apolipoprotein B)
Diseases named in the same sentence as APOB in open-access papers (continued):
Sharing a sentence is not in itself a finding about the gene and the disease.
Hypercholesterolemia (continued). "Regarding plasma ApoB levels, a significant increase of 6.9% (p < 0.05) was observed in the hypercholesterolemia group, with statistical differences with the healthy group at the end of the intervention (p < 0.001)." (PMID 37513556, 2023). "APOb is a large amphiphilic glycoprotein crucial for human lipoprotein metabolism and is characterized by the induction of hypercholesterolemia and premature coronary artery disease." (PMID 37985446, 2023). "Our study indicates that ApoB is also a potential biomarker or therapeutic target for monogenic hypercholesterolemia." (PMID 36991406, 2023). "Mipomersin drug used in treatment of familial hypercholesterolemia, which is used as antisense oligonucleotide and it acts by inhibiting apolipoprotein B." (PMID 38125244, 2023). "FCHL manifestations are heterogeneous, being able to manifest in the form of mixed hyperlipidemia, isolated hypercholesterolemia, hypertriglyceridemia, or in combination with increased levels of ApoB." (PMID 37510094, 2023). "Mipomersen, an antisense oligonucleotide inhibitor of APOB synthesis, is approved by the U. S. Food and Drug Administration as an orphan drug for use in familial hypercholesterolemia." (PMID 37209815, 2023). "Genes involved in familial hypercholesterolemia are low density lipoprotein receptor gene, apolipoprotein B, proprotein convertase subtilisin/kexin type 9, low density lipoprotein receptor adapter protein 1, other unidentified genes." (PMID 38125244, 2023). "APOB-related familial hypercholesterolemia (FH) is the most common inherited autosomal dominant hypercholesterolemia." (PMID 37510094, 2023). "Overexpression of ARL15, a member of the Adenosine diphosphate-Ribosylation Factor (ARF) family, in the liver of mouse models has also been shown to lead to hypercholesterolemia via increasing apoB level." (PMID 35371605, 2022). "Low-density lipoprotein cholesterol (LDL-C) is the primary target of lipid-lowering therapy on the management of hypercholesterolemia in the United States and European guidelines, while apolipoprotein B (apoB) is the secondary target." (PMID 35573992, 2022).
Hypercholesterolemia (continued). "In this systematic review and network meta-analysis, PCSK9 inhibitors, as adjuvant treatment in statin-treated hypercholesterolemia patients, were associated with greater reduction in atherogenic lipid level, including LDL-C, ApoB, and Lp(a)." (PMID 35444537, 2022). "Loss-of-function variants in APOB cause hypobetalipoproteinemia, normotriglyceridemic hypobetalipoproteinemia, and hypercholesterolemia—diseases affecting plasma cholesterol and ApoB levels." (PMID 34356847, 2021). "Among fathers with hypercholesterolemia, paternal and newborn ratio of apolipoprotein B to apolipoprotein A1 were significantly positively associated (q = 0.04)." (PMID 33849542, 2021). "However, it is plausible that factors that influence the stability of Tregs—hypercholesterolemia, inflammatory cytokines, local hypoxia, and changes in cellular metabolism —partially overlap with those favoring the pathogenic conversion of functionally protective FoxP3neg ApoB-specific CD4+ T cells." (PMID 33669769, 2021). "trials Mipomersen, an antisense oligonucleotide to apolipoprotein B-100, reduces lipoprotein(a) in various populations with hypercholesterolemia: results of 4 phase III." (PMID 34709306, 2021). "In the setting of hypercholesterolemia, ApoB+ T cells proliferated, expressed pro-inflammatory genes, partially lost the Treg-defining TF FoxP3, and converted into pathogenic TH1 and TH17-like cells with an only residual Treg gene signature." (PMID 33669769, 2021). "Among fathers with hypercholesterolemia, paternal LLT corrected and newborn ratio of ApoB to ApoA1 were significantly positively associated (multivariable q = 0.04)." (PMID 33849542, 2021). "Another small interfering RNA agent, inclisiran, appears to be effective in decreasing TGs and apolipoprotein B concentrations in patients with familal hypercholesterolemia, as emphasized by the results of the ORION-9 trial." (PMID 34067469, 2021). "Four patients with homozygous familial hypercholesterolemia underwent apoB kinetic analyses in 2 centers as part of a substudy of a trial evaluating the efficacy and safety of evinacumab in patients with homozygous familial hypercholesterolemia." (PMID 33691480, 2021).
Hypercholesterolemia (continued). "Evinacumab lowered LDL-cholesterol by 59±2% and increased IDL apoB and LDL apoB fractional catabolic rate in all 4 homozygous familial hypercholesterolemia subjects, by 616±504% and 113±14%, respectively." (PMID 33691480, 2021). "Mipomersen, a gapmeR targeting ApoB, has been approved for homozygous familial hypercholesterolemia." (PMID 33937351, 2021). "In the molecular genetic test, we detected some structural changes in the APOB gene in patients with a phenotype of familial hypercholesterolemia." (PMID 34834584, 2021). "We investigated apoB (apolipoprotein B) containing lipoprotein kinetic parameters in patients with homozygous familial hypercholesterolemia, before and after treatment with evinacumab." (PMID 33691480, 2021). "Another orphan drug for the treatment of familial hypercholesterolemia is mipomersen, a synthetic antisense oligonucleotide that binds to the apoB RNA, inhibiting the production of apoB." (PMID 32375792, 2020). "ApoB synthesis inhibitors have been reported to lower LDL-C levels in hypercholesterolemia subjects with LDL-C baseline average of 243.2 mg/dL." (PMID 31013851, 2019). "A study in hypercholesterolemia patients revealed that the intake of naringin (400 mg/day for 8 weeks) can cause 17% reduction in LDL-C and apoB level in plasma." (PMID 30962863, 2019). "Intake of orange juice (480 ml/day for 1 year) reduced the concentration of total cholesterol, LDL cholesterol, and apoB in patients with mild hypercholesterolemia." (PMID 30962863, 2019).
Hypercholesterolemia (continued). "Hypercholesterolemia, hypertriglyceridemia, low levels of HDL-C, and high concentrations of apolipoprotein-B are known as major risk factors in the development of chronic kidney disease (CKD)." (PMID 31505863, 2019). "Flavonoids reduce hypercholesterolemia by inhibiting hepatic synthesis of apolipoprotein B, which is a part of the VLDL and LDL lipoproteins." (PMID 29614743, 2018). "Four disease–associated genes in the proband presented VUS: APC, APOB, DSG2, and DSP, respectively associated with familial adenoma polyposis, homozygous familial hypercholesterolemia and hereditary cardiac disease." (PMID 30233642, 2018). "Heterozygous mutations in LDL Receptor, Apolipoprotein B, PCSK9, and Apolipoprotein E are linked to hypercholesterolemia." (PMID 29230236, 2017). "Already at mild hypercholesterolemia (193 mg/dL), pronounced apoB lipoprotein retention was found in the extracellular matrix in both intimal hyperplasia and the injured underlying media." (PMID 28716818, 2017). "PCSK9 inhibitors, MTP inhibitors, antisense oligonucleotide against apolipoprotein B, adenosine Triphosphate Citrate Lyase Inhibitors are experimental and sometimes promising new classes of drugs for the treatment of hypercholesterolemia." (PMID 28793863, 2017). "Low adiponectin levels and hypercholesterolemia with low high density lipoproteins (HDL) apolipoprotein AI levels and high low density lipoprotein (LDL) apolipoprotein B levels have been associated with insulin resistance and AD." (PMID 28248224, 2016). "Next, to demonstrate the general utility of the CEM effect on 2′,4′-BNA-based ASOs, we developed ASOs targeting endogenous apolipoprotein B (ApoB) mRNA, a known drug target for homozygous familial hypercholesterolemia." (PMID 26101258, 2015). "Mipomersen (Kynamro; ISIS Inc.), is an ASO that targets apolipoprotein B (apoB) in patients with familial hypercholesterolemia." (PMID 26437390, 2015). "In a study of 305 patients with primary hypercholesterolemia, atorvastatin and pravastatin reduced levels of lipoprotein particles containing apoCIII and apoB by 30%." (PMID 25120629, 2014). "Familial Hypercholesterolemia results from mutations in the LDL receptor, ApoB, PCSK9, and ApoE genes." (PMID 22111029, 2012).
Hypercholesterolemia (continued). "In the present analysis apolipoprotein B was the most significant predictor of hypercholesterolemia among all baseline measurements, including blood lipids." (PMID 18377643, 2008). "Aging, increased waist circumference, fasting blood glucose and apolipoprotein B levels were the most significant baseline predictors of hypercholesterolemia." (PMID 18377643, 2008). "Of the baseline factors, increased age, high waist circumference, fasting blood glucose and apolipoprotein B levels, were the most significant determinants of developing hypercholesterolemia." (PMID 18377643, 2008). "The present study was aimed to understand the effect of Se deficiency (0.02 ppm) and selenium supplementation (1 ppm) on apoB expression in liver during hypercholesterolemia in male Sprague Dawley rats." (PMID 16271152, 2005). "This increased level of apoB on high cholesterol feeding is due to decreased expression of LDL-R during hypercholesterolemia as observed in the present studies." (PMID 16271152, 2005). "Further, the synergistic and independent roles of Lp(a) and ApoB have been highlighted in studies exploring cases of Lp(a) and familial hypercholesterolemia, showing that Lp(a) and familial hypercholesterolemia played a synergistic role in predicting the early onset and severity of CAD." (PMID 41500124, 2026). "While controlling the high-fat diet, it can be used independently to regulate blood lipids or in combination with HMG-CoA reductase inhibitors (statins) to treat hypercholesterolemia caused by various reasons, and it can significantly reduce the levels of LDL-C, TC, and apolipoprotein B in plasma." (PMID 40989117, 2025). "ApoB is an essential structural protein for the assembly and secretion of triglyceride-rich lipoproteins and therefore remains a potential target to lower plasma cholesterol levels in hypercholesterolemia patients." (PMID 40712734, 2025). "PathogenicLDLR variants, especially in the homozygous state, portend a greatly elevated and early-onset CVD risk, necessitating vigilant management and family screening APOB and PCSK9 variants contribute to hypercholesterolemia as well, but their association with clinical CVD appears weaker." (PMID 41398288, 2025). "Among the various risk factors contributing to CVD development, familial hypercholesterolemia (FH) is of particular interest due to its solid genetic basis LDL receptor (LDL-R), apolipoprotein B-100 (APOB), and protein convertase subtilisin/kexin type 9 (PCSK9)." (PMID 40149619, 2025).